VDR (vitamin D receptor)
Diseases named in the same sentence as VDR in open-access papers (continued):
Sharing a sentence is not in itself a finding about the gene and the disease.
osteoporosis (continued). "Overall, significant correlations between VDR ApaI, VDR FokI, and osteoporosis susceptibility have been found." (PMID 33670644, 2021). "This meta-analysis only discussed genetic factors in the original literature, and the interaction of other factors such as dietary calcium and light exposure and VDR gene polymorphisms on osteoporosis was uninvolved." (PMID 33238893, 2020). "Statistically significantly decreased osteoporosis risk was found in West Asians for VDR BsmI polymorphism." (PMID 32627819, 2020). "Although many studies attempted to explore the association between VDR polymorphisms and the risk of osteoporosis." (PMID 32627819, 2020). "A total of 43 studies were included in the current meta-analysis, of which 34 studies explored the association between VDR BsmI and osteoporosis risk, 19 studies reported VDR FokI polymorphism, and four studies related to VDR Cdx2 polymorphism." (PMID 32627819, 2020). "Overall, compared with the FF and Ff genotypes, statistically significant increased osteoporosis risk was found in the VDR FokI ff genotype." (PMID 32627819, 2020). "Although several related meta-analyses have reported the associations between VDR BsmI, FokI, and Cdx2 polymorphisms and the risk of osteoporosis." (PMID 32627819, 2020). "Since then, a large number of studies have reported that VDR gene mutations (such as FokI (rs10735810), BsmI (rs1544410) and Cdx2 (rs11568820) were related to osteoporosis risk." (PMID 32627819, 2020). "This study aimed to quantitatively summarize the evidence for VDR BsmI gene polymorphism and osteoporosis risk in postmenopausal women." (PMID 33238893, 2020). "Numerous genes have been associated with osteoporosis risk and among candidate genes, the vitamin D receptor (VDR) gene, encoding a nuclear hormone receptor, was the first to be proposed as a major susceptibility locus." (PMID 32204466, 2020). "A total of six previous meta-analyses explored the association between VDR polymorphisms and osteoporosis risk." (PMID 32627819, 2020). "Six previous meta-analyses have been published to analyze VDR BsmI, FokI, and Cdx2 polymorphisms on osteoporosis risk." (PMID 32627819, 2020). "In the subgroup analysis, the VDR FokI ff genotype was significantly associated with increased osteoporosis risk in Indians and women population." (PMID 32627819, 2020). "At the overall analysis, significantly increased osteoporosis risk was found in VDR FokI ff genotype (additive model: OR = 1.49, 95% CI: 1.07–2.07; recessive model: OR = 1.47, 95% CI: 1.13–1.93)." (PMID 32627819, 2020). "A recent meta-analysis pooled the results on the associations between VDR gene variants and osteoporosis and BMD in postmenopausal women." (PMID 31887189, 2019). "In our previous work, we reported that VDR variants and physical activity have a joint effect on osteoporosis in Chinese elders." (PMID 31887189, 2019). "We evaluated gene–gene and gene–physical activity interactions of the variants of tumor necrosis factor-α (TNF-α) and vitamin D receptor (VDR) genes on osteoporosis." (PMID 31887189, 2019). "The findings indicated that VDR ApaI is linked with a decreased risk of osteoporosis in Caucasian postmenopausal women." (PMID 31887189, 2019). "Their results showed that the association between VDR polymorphisms and osteoporosis risk in postmenopausal women varied among ethnic population groups." (PMID 31887189, 2019). "A recent systematic review and meta-analysis explored the relationship between SNPs in VDR gene and osteoporosis risk in postmenopausal women." (PMID 31887189, 2019). "By contrast, Asian postmenopausal women with VDR BsmI and VDR FokI tend to have an increased risk of osteoporosis." (PMID 31887189, 2019). "Polymorphisms in the GC and VDR genes causing deficits of vitamin D (associated with several comorbidities, such as osteoporosis or skeletal muscle dysfunction, in patients with COPD), have also been connected to the frequency of exacerbations." (PMID 29927965, 2018).
osteoporosis (continued). "The VDR ApaI polymorphism decreased the risk of osteoporosis in Caucasian postmenopausal women, while in Asian populations, VDR BsmI and VDR FokI were associated with an increased risk of osteoporosis." (PMID 30150596, 2018). "Further work will also include analysis of interaction between VDR variants and other genetic markers, playing important roles in genetic predisposition to osteoporosis." (PMID 29922235, 2018). "In recent years, multiple studies have been performed to investigate correlation between VDR gene variants and osteoporosis risk, suggesting the presence of ethnic differences in the genetic association with osteoporosis." (PMID 29922235, 2018). "The aim of this study was to compare the associations of selected polymorphic variants within VDR gene with the risk of osteoporosis in Belarusian and Lithuanian postmenopausal women." (PMID 29922235, 2018). "Numerous studies have revealed the effects of several VDR gene variants on osteoporosis risk, although significant variation in different ethnicities have been suggested." (PMID 29922235, 2018). "VDR polymorphisms, Fok I and Taq I also have been studied in other common bone disorders like osteoporosis and osteoarthritis in addition to LDH and LDHD." (PMID 30356314, 2018). "Many studies investigated polymorphisms of the VDR gene in various diseases like osteoporosis, cancer, type 1 diabetes, psoriasis, and urolithiasis worldwide and also in Turkish population." (PMID 27688524, 2016). "Variations in VDR have also been associated with susceptibility to osteoporosis in humans and with reduced risk of tuberculosis and persistent hepatitis B virus infections, highlighting the importance of VDR variations in signaling and immune protection." (PMID 27293435, 2016). "Vitamin D receptor's genotypes have been associated with the development of several bone diseases as well as multiple sclerosis (MS), osteoporosis, and vitamin D-dependent rickets type II and other complex maladies." (PMID 26161090, 2015). "Larger and more rigorous analytical studies with consideration of gene-gene and gene-environment interactions are needed to further dissect the mechanisms by which VDR polymorphisms influence osteoporosis." (PMID 25364703, 2014). "Vitamin D receptor’s (VDR) genotypes have been associated with the development of several bone diseases as well as multiple sclerosis (MS), osteoporosis, and vitamin D-dependent rickets type II and other complex maladies." (PMID 25364703, 2014). "Many studies mentioned the role of VDR gene polymorphisms in disease susceptibility especially diseases related to calcium metabolism such as osteoporosis." (PMID 25606448, 2014). "To clear the relationship between osteoporosis and VDR gene polymorphisms (Fok1, Bsm1), we review the current evidence systematically." (PMID 25364703, 2014). "A series of characterized VDR gene polymorphisms, including Fok1, Bsm1, Taq1, and Apa1, have been extensively studied with regard to their association with osteoporosis, but with vise versa results." (PMID 25364703, 2014). "In our studied population, BsmI G>A genepolymorphism at the VDR locus played a significantrole in the etiology of osteoporosis; thiswas confirmed by a positive loss of BMD in thepatients." (PMID 23700563, 2013). "In consequence VDR gene is one of the major candidate genes responsible for osteoporosis and fracture risk." (PMID 23259508, 2012). "Polymorphism of the vitamin D receptor (VDR) gene was found to be associated with many diseases, including osteoporosis, hyperparathyroidism, and prostate cancer." (PMID 16507161, 2006). "Keen and colleagues examined the VDR TaqI polymorphism, associated with bone mineral density and osteoporosis, in relation to OA among postmenopausal English women." (PMID 16507122, 2006). "A recent systematic review indicates that VDR BsmI and TaqI gene variants may affect the risk of osteoporosis in Asians and Caucasians17." (PMID 40332270, 2025).
osteoporosis (continued). "Polymorphisms in COL1A1 (collagen type I alpha 1) and VDR (vitamin D receptor), implicated in osteoporosis among beta-thalassemia major (β-TM) patients, may also predispose beta-thalassemia minor (βTT) carriers to skeletal fragility." (PMID 40932695, 2025). "The association of VDR gene polymorphisms with osteoporosis is complex and inconclusive." (PMID 39859195, 2025). "They, investigated the relationship between TaqI (rs731236) and ApaI (rs7975232) polymorphisms of the VDR gene and osteoporosis in menopausal Azari women in Zanjan province, Iran, through a case–control study involving 50 osteoporotic and 50 non‐osteoporotic women confirmed by DEXA." (PMID 40831018, 2025). "Therefore, the aim of our study was to determine the effect of rs1544410 and rs11568820 polymorphisms of the VDR gene on the risk of developing osteoporosis in the Polish population." (PMID 39859195, 2025). "Moreover, some reports suggest the association of VDR variants with osteoporosis in a particular population." (PMID 39859195, 2025). "To clarify the contribution of VDR polymorphisms to genetic susceptibility to osteoporosis and osteopenia among Polish patients, especially from the West Pomeranian population, we conducted a case-control study by analyzing two well-characterized VDR polymorphisms." (PMID 39859195, 2025). "To date, the results suggest that VDR genetic variants may influence the risk of developing osteoporosis, but that this influence may vary according to population, gender, and other factors." (PMID 39859195, 2025). "Analysis of VDR gene polymorphisms may help identify individuals at increased risk of developing osteoporosis and thus implement preventive measures in target risk groups." (PMID 39859195, 2025). "The literature data on the relationship between the BsmI and Cdx2 polymorphisms of the VDR gene and the development of osteoporosis are ambiguous and sometimes contradictory, so it was decided to check their impact on the risk of developing osteoporosis in the Polish population." (PMID 39859195, 2025). "The association of several SNPs in the VDR gene with the risk of osteoporosis was investigated." (PMID 38634086, 2024). "Furthermore, genetic predisposition to osteoporosis (the VDR, COLIAI, COLIA2, and TGFB1 gene variants) can affect thalassemia trait complications." (PMID 39062234, 2024). "Further subgroup analysis focused on ethnicity revealed that ApaI, BsmI, and TaqI polymorphisms were significantly associated with the incidence of osteoporosis in Caucasians, while VDR polymorphisms BsmI and FokI were linked to an increased risk of osteoporosis among Asians." (PMID 38318147, 2024). "In T2DM patients, VDR gene polymorphisms may further increase the risk of osteoporosis, a phenomenon that has garnered considerable attention." (PMID 39897963, 2024). "Additionally, we examine the interplay between VDR and other factors, such as hormonal regulation, genetic variants, and epigenetic modifications, that contribute to osteoporosis susceptibility." (PMID 37957749, 2023). "This may throw light on the purported influence of VDR genetic variants on the therapeutic efficacy of eldecalcitol as studies have pointed out an association between VDR genetics variants and osteoporosis." (PMID 38115079, 2023). "Furthermore, several studies have recently expanded the evidence about the association of the Apa1 polymorphism of VDR with post-menopausal osteoporosis and CTIBL." (PMID 35458148, 2022). "Importantly, such gene polymorphisms affect VDR expression and function, thereby influencing the risk of developing osteoporosis." (PMID 35452412, 2022). "Gene polymorphisms in the VDR gene locus are known to be correlated with bone mass, hence its genotyping could be used to evaluate osteoporosis susceptibility." (PMID 34698098, 2021).
osteoporosis (continued). "Allelic variation of the VDR gene has been found to be causative of musculoskeletal diseases, such as osteoarthritis and osteoporosis, suggesting that VDR gene polymorphisms may underlie the development of IDD." (PMID 33776562, 2021). "However, to the best of our knowledge, this study is the first of its kind in focusing on VDR polymorphism and osteoporosis in post-menopausal women of Arab ethnicity, particularly in Saudi subjects." (PMID 34698098, 2021). "Herein, we hypothesized that genetic variation in the VDR gene could be associated with risk of osteoporosis." (PMID 34698098, 2021). "According to our results, young Japanese women with low bone mass screened by QUS may be instructed to consume more calcium depending on their VDR gene polymorphism to prevent osteoporosis." (PMID 33607983, 2021). "However, significantly decreased the risk of osteoporosis were observed in the West Asians for VDR BsmI b allele and bb genotype." (PMID 32627819, 2020). "Similarly, they were also conflicting in different studies on the associations between the VDR FokI and BsmI polymorphisms and osteoporosis risk." (PMID 32627819, 2020). "Therefore, VDR polymorphisms were associated with a variety of diseases, including bone mineral density and osteoporosis." (PMID 32627819, 2020). "In addition, when we excluded studies of low quality and HWD, a significantly decreased the risk of osteoporosis was found in the overall analysis for the VDR BsmI bb genotype." (PMID 32627819, 2020). "It indicated that possible relationship between VDR gene polymorphisms and osteoporosis may be related to gender, race, and age difference of subjects." (PMID 33238893, 2020). "However, when we performed a sensitivity analysis after excluding low quality and Hardy–Weinberg Disequilibrium (HWD) studies, significantly decreased osteoporosis risk was only found in overall population for VDR BsmI polymorphism." (PMID 32627819, 2020). "However, when we excluded studies of low quality and HWD, significantly decreased osteoporosis risk was found in overall analysis for VDR BsmI bb genotype (additive model: OR = 0.74, 95% CI: 0.56–0.99; recessive model: OR = 0.79, 95% CI: 0.63–0.98)." (PMID 32627819, 2020). "The association between VDR gene polymorphism and osteoporosis has been confirmed." (PMID 32696506, 2020). "Differences in allelic distribution by ethnicity could be partially responsible for the observed differences in the association between VDR BsmI and osteoporosis." (PMID 33238893, 2020). "Moreover, the VDR polymorphisms play an important role in the pathogenesis, prevention, diagnosis and treatment of osteoporosis and other disease such as acute ischemic stroke." (PMID 32627819, 2020). "Hence, it will be very important to investigate the association between VDR gene polymorphism and osteoporosis." (PMID 32627819, 2020). "In elderly women, we found that those carrying the CG/CC genotype of VDR rs3782905 were significantly associated with increased odds of overall osteoporosis compared with those carrying the GG genotype of VDR rs3782905 among those carrying TNF-α rs1800629 GG genotype." (PMID 31887189, 2019). "Finally, although functional data have been inconclusive for Bsm1 VDR gene polymorphism, several small studies evaluating this polymorphism have reported significant associations with osteoporosis." (PMID 26161090, 2015). "Although it is possible that QEF functions via a similar signalling cascade, the underlying mechanism between QEF and VDR, or any of these other osteoporosis-related genes, during PMOP is largely unknown." (PMID 26205885, 2015). "Likewise, 60.0% of studies reported a significant correlation between FokI VDR gene polymorphism and osteoporosis risk." (PMID 26161090, 2015). "In addition, Jia and colleagues (2013) recently found an association of the VDR BsmI polymorphism with a protective role against the development of osteoporosis in postmenopausal women using a meta-analysis of 26 studies." (PMID 26157644, 2015).
osteoporosis (continued). "A relationship between the VDR polymorphism and osteoporosis remain unclear requiring further in depth studies." (PMID 25364703, 2014). "In addition, VDR gene polymorphisms were found to be associated with osteoporosis, in which VDR polymorphisms were predictive of decreased bone mineral density in PBC patients." (PMID 23589715, 2013). "Finally, in the case of the meta-analysis for the association of VDR polymorphisms with osteoporosis, in which the authors claimed to use a log-linear model, the initially drawn conclusions are not supported." (PMID 21247440, 2011). "VDR gene polymorphisms have been associated with multiple traits and disease phenotypes like primary hyperparathyroidism, Grave's disease, Type I-diabetes mellitus and osteoporosis." (PMID 21088715, 2009). "Identification of genetic variations in the VDR gene that are associated with low BMD would enable early detection of the risk of osteoporosis, which in turn would allow the implementation of appropriate prevention that could inhibit or delay the development of osteoporosis." (PMID 39859195, 2025). "However, based on the results of other scientific studies, it can be concluded that the VDR gene and its variant rs1544410 may be a risk factor in the etiology of osteoporosis." (PMID 40149488, 2025). "This was chosen as a mouse model of RA-induced osteoporosis, considering that RA causes some damage and pro-inflammatory effects in the intestine, which may affect the regulation of VD and calcium absorption or VDR expression." (PMID 39982061, 2025). "Additionally, an in-depth exploration of the regulatory mechanisms of vitamin D receptor (VDR) gene polymorphisms in T2DM-associated osteoporosis is warranted, including the specific signaling pathways these receptor genes participate in and their correlation with insulin or glucose metabolism." (PMID 39897963, 2024). "Additionally, VDR gene polymorphisms are closely associated with T2DM-related osteoporosis." (PMID 39897963, 2024). "Furthermore, polymorphisms in the VDR gene have been linked to osteoporosis." (PMID 33413534, 2021). "The major action of the VDR endocrine system (VDES/VDR) focuses on the intestine, where it stimulates active calcium absorption and thereby allows a normal bone development (and preventing rickets) or turnover (thereby slowing down bone loss and reducing the risk of osteoporosis)." (PMID 34950831, 2021). "In conclusion, these positive findings should be interpreted with caution and indicate that significant association may most likely result from less-credible, rather than from true associations or biological factors on the VDR BsmI and FokI polymorphisms with osteoporosis risk." (PMID 32627819, 2020). "There may be different mechanisms of VDR gene polymorphisms on different types of osteoporosis." (PMID 33238893, 2020). "In addition, single nucleotide polymorphism (SNP) may affect the function of VDR and may be related with osteoporosis risk." (PMID 32627819, 2020). "Furthermore, some new studies have been published on the VDR polymorphisms and osteoporosis risk." (PMID 32627819, 2020). "Besides, it can also relieve inflammation by regulating the levels of VDR and indirectly improve the adverse effects of cerebral ischemia due to unfavorable physical activity that may cause osteoporosis." (PMID 31920636, 2019). "The VDR genotypes found in high frequency among Dené participants have been associated with decreased macrophage response to pathogens, and a number of chronic, and infectious diseases, cancer, osteoporosis, autoimmune conditions, multiple sclerosis and tuberculosis." (PMID 23185470, 2012). "The multifactorial pathogenesis of osteoporosis involves complex interactions between genetic factors and vitamin D metabolism, particularly involving key genes such as the vitamin D receptor (VDR), CYP27B1 and CYP24A1." (PMID 40831018, 2025).